INS (insulin)
Diseases named in the same sentence as INS in open-access papers (continued):
Sharing a sentence is not in itself a finding about the gene and the disease.
Insulin resistance (continued). "ROS play a crucial role in the progression of inflammatory disorders and its increased production may contribute to alterations of insulin/insulin receptor substrate signaling pathways leading to insulin resistance and inflammatory settings." (PMID 30024959, 2018). "Hepatic insulin resistance leads to subsequent decline in hepatic insulin sensitivity." (PMID 30892481, 2018). "In obesity, the hepatic insulin-Snail1 cascade is impaired due to insulin resistance." (PMID 30013137, 2018). "Additionally, ghrelin, with its connection to obesity, is related to insulin regulation and insulin resistance where it decreases insulin secretion and sensitivity ultimately leading to insulin resistance." (PMID 29743077, 2018). "Premature baboons exhibit peripheral insulin resistance and impaired insulin signaling." (PMID 30540820, 2018). "Indeed, reduced expression levels of Serpinf1 correlated with improved insulin sensitivity and reduced insulin resistance." (PMID 28575190, 2018). "Since hippocampal cognitive functioning depends on the insulin-stimulated glucose uptake, states of insulin resistance might contribute to impair memory performance." (PMID 30002734, 2018). "While the impairment in insulin signaling pathway that contributes to insulin resistance may vary between individuals, broadly speaking, impairments in proximal, or distal insulin signaling have been recognized." (PMID 30521580, 2018). "The liver, a major site of insulin action and clearance, plays an important role in maintaining glucose and insulin homeostasis, and thus is recognized as a major target of injury induced by insulin resistance and other metabolic impairments." (PMID 30333792, 2018). "In addition, GK rats displayed insulin sensitivity in the first 3 weeks after birth and became insulin resistance after 8 weeks." (PMID 30687391, 2018). "Additionally, the extent of Netrin-1 was found to be inversely related with homeostasis model evaluation of insulin resistance and plasma glucose (fasting and post-meal), fasting insulin, triglyceride, and hemoglobin A1c levels." (PMID 30320139, 2018). "To estimate if SAE extract might improve glucose tolerance, which is strongly related to insulin resistance and insulin secretion, we performed oral glucose tolerance (OGT) test." (PMID 30577476, 2018). "However, due to the contrary complications of insulin-sensitizer drugs, alternative remedies for attenuating insulin resistance in the form of dietary agents are receiving more interest among patients and practitioners." (PMID 29601521, 2018). "Some people with T2DM, however, may need greater than 0.5 units/kg/day of basal insulin in case of higher insulin resistance." (PMID 29760944, 2018). "In multiple regression models, Faecalibacterium was significantly associated with fasting glucose; Collinsella (directly) and Blautia (inversely) with insulin, and with Homeostasis-Model Assessment Insulin-Resistance, while Sutterella with C-reactive protein levels." (PMID 30111822, 2018). "Taken together, we concluded that glucose intolerance in Becn1F121A mice is not caused by insulin resistance, since Becn1F121A-mediated autophagy hyperactivation improves, rather than impairs, insulin sensitivity in insulin-responsive tissues." (PMID 29898399, 2018). "Insulin resistance characterized by increase in blood glucose (due to decreased glucose uptake by tissues) and increase in insulin levels may then also prompt an increase in β-cells intracellular glycerol concentration." (PMID 30042691, 2018). "Taken together, these findings indicate that the hyperinsulinemia, which accompanies the insulin resistance, could be mitogenic on the adrenal cortex by inducing the activation of the insulin/IGF receptors." (PMID 29495350, 2018).
Insulin resistance (continued). "Related to the index of insulin resistance in HIV patients there was a positive correlation between insulin and TG/HDL (r = 0.64, p = 0.0001), between HOMA and TG/HDL (r = 0.61, p = 0.0001) and a negative correlation was seen between adiponectin and TG/HDL (r = − 0.50, p = 0.0011)." (PMID 29434676, 2018). "In our research, the T2DM significantly enhanced insulin level of the diabetic groups, whereas AE-PS treatment reduced the insulin level, manifesting that AE-PS could mitigate the insulin resistance thereby achieving a therapeutic effect on T2DM." (PMID 30595798, 2018). "These authors also demonstrated that VATCSA was positively and negatively associated with fasting plasma glucose (FPG) and insulin concentrations, respectively, but not post-load indices of insulin resistance measured during an oral glucose tolerance test." (PMID 30169541, 2018). "Obesity can induce peripheral insulin resistance which is an impairment of cellular insulin signaling via increased inflammatory cytokines, oxidative stress, and mitochondrial dysfunction of several tissues and organs, including adipose tissue, skeletal muscle, and the liver." (PMID 30233495, 2018). "In summary, analysis of our data, based on a large number of women with PCOS, demonstrated that fasting triglycerides can be safely used instead of fasting glucose for assessment of insulin resistance, when compared to methods utilising fasting glucose and insulin." (PMID 29436386, 2018). "Berberine has been proved to reduce insulin resistance and promote insulin secretion; epiberberine, coptisine, and palmatine exert a strong effect on aldose reductase inhibition; jatrorrhizine and ferulic acid also play a certain hypoglycemic and lipid-regulating role." (PMID 30302116, 2018). "Third, we observed insulin resistance in response to MitoPQ, as measured by defective insulin-stimulated 2DOG uptake and GLUT4 translocation in cultured cells and in tissue without any demonstrable defect in proximal components of the insulin signaling pathway." (PMID 29599292, 2018). "Several in vitro and in vivo studies have shown cinnamon can reduce insulin resistance by increasing activation of the IRS/PI-3 kinase insulin signalling pathway.The extracts from cinnamon stimulate autophosphorylation of the insulin receptor and inhibit protein tyrosine phosphatase I." (PMID 30340496, 2018). "Firstly, ceramide inhibits insulin signaling by inhibiting insulin-stimulated phosphorylation of insulin receptor substrate-1 and blocking activation of protein kinase B, which stimulates the development of insulin resistance." (PMID 30275386, 2018). "For elderly women, the low islet function and insulin sensitivity, the impaired function of islet beta cells and the excessive secretion of glucocorticoid, such as placental prolactin, are easy to induce insulin resistance." (PMID 30087863, 2018). "In addition, although leptin levels are not significantly correlated with metabolic parameters of obesity and T2DM, strong correlations of leptin levels with insulin levels and with indexes of insulin resistance/sensitivity and β cell function." (PMID 29785210, 2018). "High fructose intake may cause hyperglycemia, increase oxidative stress, and decrease insulin sensitivity, leading to insulin resistance in liver, skeletal muscle, and adipose tissues." (PMID 29342975, 2018). "It was demonstrated that the hypercaloric diet models showed the same metabolic profile observed in humans, such as increased levels of insulin, insulin resistance, hyperglycemia, hyperleptinemia, glucose intolerance, and increased levels of visceral white adipose tissue." (PMID 30515333, 2018). "High insulin and glucose concentrations are direct consequences of insulin resistance." (PMID 29732028, 2018).
Insulin resistance (continued). "Therefore, consistent with other physiological models of insulin resistance, such as the diet-induced obese mouse, insulin-stimulated GLUT4 translocation was sensitive to MitoPQ under conditions where other insulin/Akt-regulated processes were unaffected." (PMID 29599292, 2018). "Notably, the AGEs not only destroy insulin-producing cells but also develop insulin resistance, a major symptom of T2DM." (PMID 30046616, 2018). "It is unclear whether insulin resistance occurs simultaneously in all these tissues or whether insulin resistance is tissue specific." (PMID 29535167, 2018). "In these mice, serum concentrations of leukocyte cell–derived chemotaxin 2 (LECT2), which is known to induce insulin resistance in skeletal muscle, were elevated, and insulin signaling in muscle, as determined by the phosphorylation levels of Akt and p70 S6 kinases, tended to be decreased." (PMID 29630667, 2018). "Numerous risk factors including increased age, unhealthy dietary intake, and obesity all lead to an oxidative environment that may modify insulin sensitivity either via the elevation of insulin resistance or the impairment of glucose tolerance." (PMID 29643982, 2018). "Type 2 diabetes is characterized by insulin resistance accompanied by defective insulin secretion." (PMID 29682407, 2018). "In this regard, prediabetes may represent a suitable model in that it is not characterized by overt hyperglycemia, which is the final consequence of insulin resistance as well as impaired insulin secretion." (PMID 30513818, 2018). "Thus, we examined the responses of insulin-target tissues, such as liver and muscle, using matured ArKO male mice, which develop systemic insulin resistance." (PMID 30211334, 2018). "The pathology of hyperinsulinemia-induced insulin resistance is associated with impaired Ser/Tyr phosphorylation of IRS-1 and IRS-2 that impairs their interactions with cytoplasmic domain of insulin receptors and deregulate the insulin signaling." (PMID 29786669, 2018). "In addition, long-term exposure to FFA results in suppressed glucose-stimulated insulin secretion (GSIS) and reduced insulin biosynthesis, eventually leading to adaptive decline of β-cell mass and/or function as a compensatory response to insulin resistance." (PMID 30241400, 2018). "Moreover, PPAG has been recently shown to improve fasting blood glucose levels, glucose tolerance, insulin levels and insulin-resistance in OBIR rats." (PMID 29642387, 2018). "Apart from an intra-pancreatic impact on glucose homeostasis, we speculate that TEA could possibly diminish peripheral insulin resistance, thereby reducing the need for insulin secretion." (PMID 30468105, 2018). "Therefore, the association of chemerin with metabolic parameters, including assessment of fasting glucose, insulin levels, homeostasis model assessment of insulin resistance (HOMA-IR) and lipid profiling should be assessed in future studies." (PMID 29915268, 2018). "In response to low-level inflammation from DIO, extracellular matrix remodeling may contribute to the onset of insulin resistance, thereby inducing collagen synthesis and muscle fibrosis, and contributing to decreased insulin signaling." (PMID 29527173, 2018). "In addition, honey enhances insulin sensitivity that further stabilizes blood glucose levels and protects the pancreas from overstimulation brought on by insulin resistance." (PMID 30072671, 2018). "The reduction of liver glycogen due to lack of insulin or insulin resistance is often linked with enhanced activity of glycogen phosphorylase to improve glycolysis, eventually resulted in hyperglycemia." (PMID 30533432, 2018). "DJP and its phenols components showed anti-inflammation and antioxidant activities in vitro; the present study demonstrated that DJP (in a dose of 100 mg/kg) can significantly decrease the blood glucose, LDL-C, insulin resistance and increase serum INS level in db/db mice." (PMID 30544624, 2018).
Insulin resistance (continued). "Any other precipitants like increased insulin resistance due to stress, extended fasting, or ambitious decrease in insulin secretagogue or insulin could transform the patient from this drug-induced ketogenic state to ketoacidosis." (PMID 30369948, 2018). "One key paper could show that endothelial insulin resistance, as measured by insulin’s ability to stimulate eNOS phosphorylation, occurs weeks before detectable systemic and in particular muscle or adipose tissue insulin resistance." (PMID 29209827, 2018). "Theoretically, increased insulin secretion could compensate for insulin resistance and could maintain normal plasma glucose levels for 10 years before the onset of clinical T2DM." (PMID 29568712, 2018). "Moreover, the adipose tissue is recognized as a primary site of insulin resistance and suppression of insulin signaling in adipocytes suffering from insulin resistance reduces glucose transport and metabolism." (PMID 29394254, 2018). "Despite lacking any association between monocyte subsets and insulin resistance, fetuin-A is a negative contributor to the insulin sensitivity." (PMID 29582352, 2018). "This suggests that the adipocyte utilises transcriptional cascades to respond to the oxidative stress occurring during the development of insulin resistance, but the primary site(s) by which oxidative stress impairs insulin action are likely to occur post-transcriptionally." (PMID 29379070, 2018). "It is characterized by insulin resistance and impaired insulin secretion." (PMID 30598071, 2018). "During insulin resistance, excess glucose is not sufficiently absorbed by cells even in the presence of insulin, thereby causing an increase in the level of blood sugar." (PMID 29986479, 2018). "ILG improved insulin resistance by lowering plasma glucose and insulin levels." (PMID 30360437, 2018). "We found a significant relationship between insulin resistance and sympathetic response to moxonidine, suggesting large clinical trials are needed to evaluate the effectiveness of this medication potentially targeting the most insulin resistant PCOS cases." (PMID 30410448, 2018). "In addition, chronic hyperglycemia decreases insulin secretion from pancreatic β-cells and increases insulin resistance." (PMID 29772703, 2018). "In addition to ICAM-1, other studies have reported adipocyte-derived EVs (CD14+) to interfere with insulin signaling in both the liver and skeletal muscle via transfer of adipokine content, thereby inducing insulin resistance." (PMID 30018986, 2018). "An improvement in insulin signaling in ucOC-treated mice, as seen by an increase in the IRβ subunit and Akt Ser-473 phosphorylation, demonstrates that ucOC rescues high-fat-diet-induced insulin resistance in mouse aorta." (PMID 30287742, 2018). "We evaluated serum high sensitivity C reactive protein (hsCRP), tumor necrosis factor alpha (TNF-α), chemerin, nitrite and nitrate (NOx), total oxidant status (TOS), total antioxidant response (TAR), fasting blood glucose, insulin, and homeostasis model assessment of insulin resistance (HOMA-IR)." (PMID 30200422, 2018). "Furthermore, there was a trend toward improved insulin sensitivity, estimated by homeostasis model assessment of insulin resistance (HOMA-IR), and significantly reduced fasting triglyceride levels in the first group." (PMID 29673211, 2018). "However, insulin resistance promotes FoxO1 activation by reducing insulin signaling, resulting in dephosphorylation of the FoxO1 allowing its entry into the nucleus." (PMID 30424007, 2018). "The decrease in insulin resistance was related to loss of visceral fat, independent of changes in BMI, while changes in glucose-induced insulin secretion were related to changes in BMI only." (PMID 29425120, 2018). "In addition, the vitamin D supplementation therapy would decreases fasting plasma glucose, serum insulin concentrations, and homeostasis model assessment-estimated insulin resistance (HOMA-IR)." (PMID 30687119, 2018).
Insulin resistance (continued). "Fructose impairs insulin signaling and thereby leads to hepatic and peripheral insulin resistance." (PMID 30081580, 2018). "Thiazolidinediones (TZDs), pioglitazone and rosiglitazone, are potent and selective receptor agonist of peroxisome proliferator–activated receptor-γ (PPAR-γ) nuclear receptors that improve insulin sensitivity in muscle, adipose and hepatic tissue; reducing systemic insulin resistance." (PMID 30355995, 2018). "This study demonstrated that acute increases in serum ferritin and hemoglobin following blood transfusion in patients with thalassemia might contribute to an increase in insulin secretion and to a trend towards increased insulin resistance." (PMID 28739553, 2018). "Among Danes of Caucasian ethnicity, the genetics of birth weight and ponderal index appear to be partly shared with the genetics of adult insulin resistance, supporting the fetal insulin hypothesis." (PMID 30514227, 2018). "In particular, lipid-induced insulin-resistant muscle EVs transferred miR-16 to beta cells regulating Ptch1, a receptor involved in the sonic hedgehog pathway and suggested to exert a significant role in insulin resistance development." (PMID 29808089, 2018). "Studies have shown that saturated fatty acid rich-diets, besides inducing obesity, are able to increase blood glucose levels due to the suppression of insulin signaling by TNFα and other inflammatory cytokines, as well as the excess FA, triggering insulin resistance." (PMID 29320433, 2018). "The result demonstrated that GD could efficiently restrain an abnormal increase of insulin secretion and ameliorate the insulin resistance." (PMID 30337946, 2018). "Indeed, multiple studies have demonstrated a clear relation between depression and insulin resistance, which is the precursor to diabetes when cells fail to respond to the normal actions of insulin." (PMID 30622489, 2018). "Indeed glypican-4 has been considered a novel adipokine that boosts insulin signaling and, interestingly glypican-4 levels are significantly increased in obese patients with insulin resistance." (PMID 30061880, 2018). "However, our obese subjects had normal blood glucose, but had insulin resistance and high fasting blood insulin." (PMID 30388806, 2018). "In addition, resveratrol can also relieve insulin resistance and increase insulin secretion in some models." (PMID 30273360, 2018). "Likewise, human efficacy trial for insulin sensitivity/resistance by different test like HOMA-insulin resistance, QUIKI, and Matsuda should be conducted to unveil the mechanistic concerns." (PMID 30021615, 2018). "Furthermore, obese children and adolescents presented with greater levels of insulin resistance, as reflected by the elevated glucose, insulin and HOMA-IR values." (PMID 30572569, 2018). "Experiments measuring hepatic DAGs content and hepatic insulin sensitivity in humans have indicated that DAGs strongly correlate with hepatic insulin resistance, whereas other potential mediators of hepatic insulin resistance (such as ceramides) show an inconsistent relationship." (PMID 30692925, 2018). "A following more detailed study, including patients with active rheumatoid arthritis and high insulin resistance, confirmed these findings while it also proved restoration of mediators' phosphorylation in the insulin signaling cascade, after 12 weeks of treatment with anti-TNF agents." (PMID 29576769, 2018). "In addition, it seems that insulin resistance modifies the effect of insulin on the vascular wall and has anti-atherogenic effect in the insulin sensitive state and pro-atherogenic effect in the insulin resistant state." (PMID 29732028, 2018). "Moreover, BW was strongly correlated with insulin resistance as expressed by fasting insulin levels (r = 0.87, P < 0.001), HOMA-IR (r = 0.88, P < 0.001) and ITT AUC (r = 0.77, P < 0.001)." (PMID 30036374, 2018). "Insulin resistance is generated by the impairment of insulin signaling in different tissues." (PMID 30380669, 2018).